EGFR (epidermal growth factor receptor)
Diseases named in the same sentence as EGFR in open-access papers (continued):
Sharing a sentence is not in itself a finding about the gene and the disease.
lung cancer (continued). "Further studies on RCCs with prior antiangiogenic therapy have to investigate if MET amplification is seen in therapy resistant RCCs, resembling a resistance mechanism evident in lung cancers with EGFR activating mutations treated with Gefitinib." (PMID 27894094, 2017). "At present, the detection of activating or resistance mutations in EGFR in plasma samples can be performed in the clinical care of patients with advanced stage lung cancer according to the different practices available." (PMID 28805673, 2017). "The loss of the gene encoding constitutively activated mutant EGFR is required for resistance to EGFR-TKIs in lung cancer cells." (PMID 29050315, 2017). "The multivariate analysis showed smoking status was most significant predictor for EGFR mutation in lung cancer." (PMID 28881771, 2017). "Several papers have reported relationship between FDG uptake in lung cancer and EGFR and KRAS gene mutations." (PMID 28881771, 2017). "Ectopic expression of ZEB1 in EGFR-mutated lung cancer cells inhibited cell growth by increasing miR-200c target Notch1, which repressed ErbB3 promoter activity and the expression of ErbB3." (PMID 28587302, 2017). "The effect of statins in reducing the risk of death was then evaluated in subpopulations of lung cancer patients with EGFR-TKI therapy." (PMID 28158206, 2017). "Germline mutations in multiple genes—particularly in EGFR—have been reported that increase risk of lung cancer in small numbers of families exhibiting various rare cancer syndromes." (PMID 28106732, 2017). "Here we report the existence of a special subpopulation of patient-specific-CAFs that augment the sensitivity of EGFR gene mutation-positive lung cancer to the EGFR-tyrosine kinase inhibitor (EGFR-TKI), gefitinib." (PMID 28429795, 2017). "In this study, we investigate the parallel emergence of EMT clones dependent on FGFR1 and clones with MET-amplification during erlotinib-resistance development in the EGFR-mutated lung cancer cell line HCC827." (PMID 28368392, 2017). "Another EGFR-triple-mutated lung cancer xenograft model using MGH121-res2 cells showed not only a growth inhibition effect with brigatinib but also a significant tumour shrinkage without toxicity with a combination treatment of cetuximab and brigatinib." (PMID 28287083, 2017). "Our study used tissues obtained from mostly early stage lung cancer patients from Korea, where there is a high percentage of EGFR mutation positive lung cancer." (PMID 29029422, 2017). "Several previous studies have assessed single nucleotide polymorphisms (SNPs) in the EGFR gene that is implicated in human tumors, such as breast cancer, lung cancer and prostate cancer." (PMID 28938685, 2017). "We completed a study comparing pemetrexed–platinum combination versus oral TKI in EGFR mutation-positive patients in lung cancer." (PMID 29104613, 2017). "An important and well-established target for lung cancer treatment is the occasionally mutated epidermal growth factor receptor (EGFR)." (PMID 28405842, 2017). "For instance, the patients with EGFR mutated lung cancer are benefit from erlotinib and gelfitinib, but if EFGR harboring T790 M mutation, then resistant to these drugs." (PMID 28882180, 2017). "To get further evidence that lung cancer cells cultured in 3D react differently to EGFR kinase inhibitors, we treated three further lung cancer cell lines expressing mutated EGFR variants with gefitinib and erlotinib." (PMID 29296175, 2017). "Non-small cell lung cancer (NSCLC) accounts for 83% of all lung cancer cases with epidermal growth factor receptor (EGFR)-activating mutations frequently found in these tumors (10–15% in Caucasians, 50% in Asians)." (PMID 27786612, 2017). "We tested the viability of human lung cancer cell lines upon treatment with the 3rd-generation EGFR TKI AZD9291 (osimertinib), which has been shown to be cytotoxic to lung cancer cells harboring the EGFR T790M mutation." (PMID 28422737, 2017).
lung cancer (continued). "Although lung cancer patients harboring EGFR mutations benefit from treatment with EGFR‐tyrosine kinase inhibitors (EGFR‐TKI), most of them rapidly relapse." (PMID 28003335, 2017). "A summary from 66 publications showed 96 (6%) doublets in 1621 EGFR-mutated lung cancers, including several tumors which were indeed complex exon 19 deletion." (PMID 29228562, 2017). "Resistance to treatment due to mutations in EGFR hindered the extensive usage of these agents in lung cancer patients." (PMID 29234489, 2017). "The phase III ARCHER trial randomized patients with EGFR-mutated lung cancer to first-line treatment with either dacomitinib, a second generation EGFR-targeted TKI or gefitinib as the standard of care." (PMID 29250201, 2017). "Multivariate analysis showed that being a never-smoker was the most significant factor (p < 0.001) for the EGFR mutations in lung cancer overall." (PMID 28881771, 2017). "EGFR mutations or ALK rearrangements in lung cancer, BRAF V600E mutations in metastatic melanoma and breast cancer patients harbouring HER2 amplifications are examples of therapeutic biomarkers routinely used in the adult population." (PMID 29340109, 2017). "EGFR mutations are significant predictors of treatment response to TKIs, but unfortunately, only 15 % of all lung cancers are expected to be sensitive." (PMID 29312591, 2017). "Although many epidermal growth factor receptor (EGFR)-mutated lung cancer patients initially benefit from the EGFR-inhibitor erlotinib, all acquire resistance." (PMID 28368392, 2017). "Although EGFR mutations have been reported to predict sensitivity to EGFR tyrosine kinase inhibitors in lung cancer, little is known about the impact of EGFR amplifications in either for selecting patient to anti-EGFR treatment or as a role in resistance." (PMID 28915719, 2017). "In conclusion, we showed that triplet therapy with afatinib, cetuximab, and bevacizumab repeatedly induced pathological CR in lung cancers harboring EGFR T790M mutations with tolerable toxicity in preclinical xenograft models." (PMID 28388009, 2017). "In lung cancers with EGFR-activating mutations, anti-EGFR therapies, including gefitinib, erlotinib, and afatinib, have been shown to improve progression-free survival and were approved as first-line options." (PMID 28860487, 2017). "Summary of studies of the association between family history and EGFR activating mutations or survival in lung cancer patients." (PMID 28486527, 2017). "In a lung cancer model, inhibition of β-catenin was shown to enhance the anticancer effect of EGFR-TKI in EGFR-mutated cells." (PMID 29143801, 2017). "The study was the first to directly compare these RT-PCR and MS tests despite both being commercially available and widely used in clinical practice for the detection of EGFR gene mutations in lung cancer patients." (PMID 29254176, 2017). "An association of EGFR activating mutation with a family history of lung cancer in first-degree relatives was evaluated with multivariate logistic regression analysis, and its association with survival was estimated with Cox’s proportional hazards model." (PMID 28486527, 2017). "Subsets of lung cancers and glioblastomas harbor activated point mutants or splice variants of EGFR, but such alterations are rare in breast cancer where EGFR is activated primarily by overexpression of the wild type protein." (PMID 28423644, 2017). "The test for epidermal growth factor receptor (EGFR) mutations has significant prognostic relevance in lung cancer patients, particularly in those with advanced adenocarcinoma." (PMID 28830378, 2017). "We previously established afatinib-resistant sublines from the human lung cancer cell line PC9 that harbors an activating EGFR mutation." (PMID 29050315, 2017). "The most striking result we obtained was in the human xenograft containing a mutation in EGFRL858R, which is the most common single mutation in EGFR mutant lung cancers." (PMID 29069801, 2017).
lung cancer (continued). "Circulating tumor DNA (ctDNA) is a promising biomarker for noninvasive epidermal growth factor receptor (EGFR) mutations detection in lung cancer patients, but the existing methods have limitations in sensitivity or in availability." (PMID 28829813, 2017). "Although some experts believe that the benefits of these agents have plateaued, the promising results of an erlotinib/bevacizumab combination in EGFR-mutated lung cancer have proven otherwise." (PMID 28424759, 2017). "This is the first study to distinguish among the effects of PORT on pN2 lung cancer of different pathological types, EGFR mutations, and sexes." (PMID 27835914, 2017). "Contrast this study to the study of erlotinib versus chemotherapy for the first-line treatment of patients with lung cancer harboring an EGFR activating mutation." (PMID 28854908, 2017). "Although targeted therapy, using tyrosine-kinase inhibitors such as erlotinib (Erlo), has shown therapeutic benefit, only 15 % patients with mutated epidermal growth factor receptor (EGFR) in lung cancer cells are sensitive." (PMID 29312591, 2017). "H1975, an EGFR-driven human lung cancer cell line, carries both a primary mutation in EGFR (L858R) and a second site mutation in EGFR (T790M) that confers resistance to small molecule EGFR TKIs such as erlotinib." (PMID 27786612, 2017). "Ongoing studies recruiting families is rarer, but the INHERIT EGFR study is looking for patients with EGFR mutations in their lung cancer tumors to determine if these mutations are somatic or were inherited in the germline." (PMID 28106732, 2017). "EGFR and phosphorylated (p)EGFR protein levels in mutated human lung cancer cell lines were analyzed by western blotting." (PMID 28422737, 2017). "One possible explanation is that both PI3K/Akt and RAF/RAS/ERK pathways are the downstream signaling molecules of EGFR signaling, which is associated with the occurrence and development of lung cancer." (PMID 28938613, 2017). "Compound 18 along with erlotinib, a TKI exhibited a synergistic effect on EGFR mutated lung cancer cell line." (PMID 29088782, 2017). "It is also well recognized that lung cancer cells carrying wild-type EGFR are less sensitive to EGFR TKIs than lung cancer cells with EGFR activating mutations." (PMID 28881608, 2017). "A wide range of normal and tumor cells express EGFR, and deregulation of EGFR is associated with epithelial tumors, such as pancreatic cancer, lung cancer, head and neck squamous cell carcinoma, colorectal cancer, and breast cancer." (PMID 29312333, 2017). "A number of generations of inhibitors (e.g., erlotinib, gefitinib, afatinib, and osimertinib) have been developed to target specific EGFR mutations that are frequently found in untreated lung cancer and recurrent lung cancers." (PMID 28472989, 2017). "For the selection, we eliminated the BsAbs that resulted in loss of binding, increases of lung cancer cell proliferation, and increases in EGFR and c-Met phosphorylation." (PMID 27786612, 2017). "Although a few studies have described an association of family history of lung cancer with EGFR activating mutation, their impact on survival of lung cancer patients is unclear." (PMID 28486527, 2017). "For example, mutated BRAF is seen in melanomas, ALK raises suspicion for lung cancer, and EGFR has been described in multiple cancer types including lung, colorectal, pancreatic, breast, and thyroid." (PMID 28054963, 2017). "This study confirms that family history of lung cancer in first-degree relatives is significantly associated with the presence of EGFR activating mutation." (PMID 28486527, 2017). "Tyrosine kinase inhibitors can be used to treat lung cancers associated with EGFR mutations, but tumors eventually become resistant, and effective treatments for KRAS-induced cancers are currently lacking." (PMID 29340023, 2017).
lung cancer (continued). "Gefitinib was also shown response in phase II clinical trials with better clinical response in lung cancer patients harboring activating mutations in the tyrosine kinase domain of the EGFR." (PMID 29069801, 2017). "We investigated the relevance between the USP24 level and the EGFR mutation in clinical lung cancer specimens and found that patients with the EGFR mutation were more highly correlated with reduced USP24 expression." (PMID 27991932, 2017). "Osimertinib has been approved for the treatment of EGFR‐mutated lung cancer that has acquired EGFR‐TKI resistance due to the T790M mutation." (PMID 29125233, 2017). "More importantly, miR-370 over-expression inhibited the proliferation, clonogenicity, wound healing and invasion of lung cancer cells in vitro, which were associated with reduced levels of EGFR and HIF-1α expression and the ERK1/2 and AKT activation." (PMID 29152147, 2017). "Longitudinal sampling of five lung cancer cases showed distinct changes in ctDNA mutation portraits that are consistent with cancer progression or response to EGFR drug treatment." (PMID 28472989, 2017). "The lung cancer patients harboring EGFR del19 mutation have been found to be more susceptible to EGFR-TKIs than those harboring exon 21 L855R mutation." (PMID 27926500, 2017). "Certain RTK gene alterations, such as ERBB2 amplifications in breast cancer and EGFR mutations in lung cancer, are excellent therapeutic targets and used in clinical practice." (PMID 28099935, 2017). "Since the EGFR mutation is a clinical significant molecular characteristic of lung cancer, the effect of Quinalizarin on the radiosensitivity of the EGFR mutant adenocarcinoma cells H1975 and HCC87 was also explored in the current study." (PMID 29170453, 2017). "The present study offers a new strategy to increase the initial clinical response rate in EGFR‐mutated lung cancer patients by providing a molecular rationale for using EGFR‐TKI in combination with AKT inhibitor in patients harboring high RHOB tumor levels." (PMID 28003335, 2017). "In Europe, the first reports of lung-cancer–specific EGFR mutations were described in Italy, and showed EGFR mutations in 10% of 375 lung adenocarcinomas, whereas in Spain it was described a rate of EGFR mutations of 16.6%." (PMID 28881604, 2017). "Overexpression of miR-1343-3p and reduced expression of miR-671-3p, miR-103a-3p, let-7e, and miR-342-3p were especially distinctive in the ALK-rearranged lung cancer compared with EGFR-mutated and KRAS-mutated lung cancer." (PMID 29189709, 2017). "These “driver” mutations increase the kinase activity of EGFR, leading to EGFR overexpression and uncontrolled lung cell division and eventually lung cancer." (PMID 28747773, 2017). "Clinical evidence further confirms that high expression of MCT-1 is associated with an increase in YY1, EGFR and MnSOD expression, accompanied by tumor recurrence, poor overall survival and EGFR mutation status in patients with lung cancers." (PMID 28394354, 2017). "Several studies suggest that KRAS mutations should be known prior to using EGFR-TKI therapy for lung cancer patients." (PMID 28415658, 2017). "An acquired HER2T798I “gatekeeper” mutation, homologous to the EGFRT790M mutation in EGFR inhibitor-resistant lung cancer, was recently identified in a HER2-mutant breast cancer patient following progression on neratinib." (PMID 29371993, 2017). "In this study, we used CRISPR/Cas9 nucleases-assisted genome editing to generate lung cancer cell lines harboring the EGFR T790M mutation." (PMID 28422737, 2017). "Compound 18 was also shown to have a synergistic effect with erlotinib on EGFR mutated lung cancer cell lines." (PMID 29088782, 2017). "Recently, the Korean Food and Drug Administration approved the PNA ClampTMEGFR Mutation Detection kit (PANAGENE Inc., Daejeon, Korea) as a standard screening method for EGFR mutation in lung cancer patients." (PMID 29029416, 2017).
lung cancer (continued). "Unlike classic EGFR mutations, there is a paucity of data regarding the EGFR-TKI sensitivity of patients with lung cancers expressing less common EGFR mutations." (PMID 29285266, 2017). "The PI3K/AKT pathway is known to control the oncogenic addiction observed in EGFR‐mutated lung cancer, and its activation has been shown to be a crucial event in the resistance to targeted therapies." (PMID 28003335, 2017). "Meanwhile, discovered in 2004, EGFR mutation is the first molecular alteration in lung cancer that is shown to confer sensitivity to specific targeted therapies, namely TKIs." (PMID 28430586, 2017). "First, the interaction between epidermal growth factor receptor and S100A family can promote angiogenesis and metastasis in a variety of cancers, whereas the percentage of EGFR mutations is relatively small in these 2 types of lung cancers." (PMID 28498804, 2017). "The EGFR 19 deletion mutation is associated with prolonged survival in patients with lung cancer, with a median survival of approximately 92 months." (PMID 29110716, 2017). "A lower risk of depression was observed in lung cancer patients with monthly income NT$15,841 to $25,000, brain metastasis, CT+RT, RT, and EGFR-TKI." (PMID 28489782, 2017). "Previous studies have demonstrated that both PET/CT and serum tumor markers showed values in evaluating the histological type and EGFR mutation status of lung cancer." (PMID 28877268, 2017). "We retrospectively reviewed molecular pathology reports of 959 cases with lung cancer analysed for epidermal growth factor receptor mutations." (PMID 28832323, 2017). "We reviewed the National Lung Cancer database (Taiwan) to assess the impact of smoking on the EGFR mutation rate and survival in advanced lung adenocarcinoma patients during 2011 and 2014 retrospectively." (PMID 29228697, 2017). "In a randomized phase II trial, the erlotinib and bevacizumab combination significantly prolonged progression‐free survival compared to erlotinib alone in patients with lung cancers harboring EGFR mutations." (PMID 28388009, 2017). "Our data implies possible low PD-L1 expression in TKI-refractory lesions without T790M mutation, and that can be one of the molecular mechanisms that attenuates the efficacy of PD-1/PD-L1 targeting agents in lung cancer patients with EGFR mutations." (PMID 29119113, 2017). "EGFR mutation and EGFR tyrosine kinase inhibitors (EGFR-TKIs) resistance also exist in DS with lung cancer." (PMID 28903458, 2017). "Currently, epidermal growth factor receptor (EGFR) mutation is the most common type of gene mutations detected in Asian populations with lung cancer, and EGFR is identified as the therapeutic target of EGFR tyrosine kinase inhibitors (TKIs)." (PMID 27926500, 2017). "For example, osimertinib is highly active in patients with lung cancer with the EGFR T790M mutation who experience disease progression during prior therapy using EGFR-TKIs." (PMID 29050315, 2017). "In this study, we analyzed PD-L1 protein expression in lung cancer cell lines with EGFR mutations prior to and after acquisition of resistance to EGFR tyrosine kinase inhibitors (TKIs)." (PMID 29119113, 2017). "Briefly, plasma samples were collected from 64 EGFR exon 19 deletion, 36 EGFR p.L858R mutation, and 53 EGFR wild-type patients in the Department of Lung Cancer and 41 healthy controls from the Physical Examination Centre at our institution." (PMID 28496005, 2017). "This trial was commenced before a general adoption of EGFR mutations for selection of lung cancer patients to EGFR inhibitor treatment." (PMID 27924059, 2017). "We carried out this meta-analysis to evaluate the clinical efficacy of icotinib in lung cancer patients with different EGFR mutation status." (PMID 28430623, 2017). "Only one doublet consisting of exon 19 deletion and p.L858R was reported among 1621 EGFR-mutated lung cancers." (PMID 29228562, 2017).